RGS2 (regulator of G protein signaling 2)
Diseases named in the same sentence as RGS2 in open-access papers (continued):
Sharing a sentence is not in itself a finding about the gene and the disease.
RGS2 also shares sentences with these, for which no sentence is quoted: Huntington disease (4 papers); acute myeloid leukemia (3); cardiac arrhythmia (2); essential hypertension (2); hypertrophy (2); idiopathic pulmonary fibrosis (2); panic disorder (2); Type 2 Diabetes (2); Ureteral obstruction (2); age (1); atrial tachycardia (1); Atrophic Gastritis (1); attention deficit-hyperactivity disorder (1); cognitive decline (1); dementia (1); gastritis (1); gestational diabetes mellitus (1); Glucose intolerance (1); glucose metabolism disorder (1); Hypercholesterolemia (1); Hypoinsulinemia (1); infiltrating ductal carcinomas (1); invasive breast carcinoma (1); irritable bowel syndrome (1); left ventricular dilation (1); liver cancer (1); lymphoma (1); mental disorder (1); multiple sclerosis (1); neural tube defect (1).
A further 12 diseases each share a sentence with RGS2 in 1 paper.